UGT1A1 (UDP glucuronosyltransferase family 1 member A1)
Diseases named in the same sentence as UGT1A1 in open-access papers (continued):
Sharing a sentence is not in itself a finding about the gene and the disease.
lung adenocarcinoma (3 papers, 2018 to 2022). A carcinoma that arises from the lung and is characterized by the presence of malignant glandular epithelial cells. "Those with the TA7 allele or with genotypes associated with reduced or low UGT1A1 activity had an increased risk for lung adenocarcinoma." (PMID 35328047, 2022). "The UGT1A1 gene polymorphism (rs8175347) showed a significant association with lung squamous cell carcinoma and lung adenocarcinoma in the population of the Amazon region." (PMID 35328047, 2022). "Importantly, this study is one of the few that has investigated the association between how polymorphism that can alter the length of the UGT1A1 gene promoter and the risk of lung adenocarcinoma and squamous cell carcinoma." (PMID 35328047, 2022).
lymphoma (3 papers, 2018 to 2025). A malignant (clonal) proliferation of B- lymphocytes or T- lymphocytes which involves the lymph nodes, bone marrow and/or extranodal sites. "One study has related UGT1A1*6 (rs4148323) with the response to (CDE-11), a treatment for lymphoma that includes Dexamethasone, Irinotecan, and other compounds." (PMID 40149530, 2025).
mucositis (3 papers, 2020 to 2023). Mucositis is inflammation and damage of the mucous membranes lining the mouth and other parts of the gastrointestinal (GI) tract. "Patients with UGT1A1*28 mutations also have an increased chance of mucositis." (PMID 35340156, 2022). "Our research found an increased risk of vomiting and mucositis, which may indicate that in patients with UGT1A1 mutations, we should pay more attention to these two often overlooked adverse reactions related to CPT-11 use in daily clinical practice." (PMID 35340156, 2022). "In addition, CPT-11 administration to liver-specific UGT1A1-deficient mice resulted in the same mortality as that in wild-type mice, whereas CPT-11-induced diarrhea and intestinal mucositis were more severe in gut-specific UGT1A1-deficient mice than in wild-type mice." (PMID 37085597, 2023). "In line with this study, and after adjusting for clinicopathological covariates and the UGT1A1*28 genotype in a larger sample, we found that patients with the CC genotype for the ABCB1 rs1128503 variant were at highest risk of diarrhea (P=0.014) and mucositis (P=0.002)." (PMID 32695000, 2020).
neuroblastoma (3 papers, 2016 to 2022). Neuroblastoma (NB) is the most common solid, extracranial childhood tumor. "Finally, higher bilirubin levels predicted by the non-UGT1A1 SNPs were inversely associated with risk of Hodgkin’s lymphoma (OR 0.64, 95% CI 0.42–0.99), while null results were observed for melanoma or neuroblastoma risk." (PMID 33671849, 2021). "Studies in children with neuroblastoma explored the association between IRT-related ADRs and UGT1A1, suggesting that UGT1A1*28 poor metabolizers could be at risk of ADRs." (PMID 27618021, 2016). "In conclusion, the results of our study suggest that IREC is a promising second‐line chemotherapy for refractory or relapsed neuroblastoma and is well tolerated regardless of UGT1A1 genotype." (PMID 35233973, 2022).
ovarian carcinoma (3 papers, 2016 to 2021). A malignant neoplasm originating from the surface ovarian epithelium. "Higher bilirubin levels predicted by the UGT1A1 SNP were weakly inversely associated with risk of ovarian cancer overall and serous ovarian cancer with ORs per 1-SD increment equal to 0.96 (95% CI 0.92–1.00) and 0.94 (95% CI 0.90–0.98), respectively." (PMID 33671849, 2021). "We are not aware of other studies investigating either circulating bilirubin levels or the UGT1A1 polymorphism in relation to ovarian cancer risk, and further studies are warranted." (PMID 33671849, 2021). "In contrast, we observed a positive association between bilirubin levels predicted by non-UGT1A1 SNPs and risk of ovarian cancer overall and serous ovarian cancer with ORs per 1-SD increment equal to 1.10 (95% CI 1.00–1.21) and 1.12 (95% CI 1.00–1.24), respectively." (PMID 33671849, 2021). "The presence of UGT1A1*28 results in an increased risk of ovarian cancer." (PMID 31895688, 2020).
rectal cancer (3 papers, 2020 to 2023). A primary or metastatic malignant neoplasm that affects the rectum. "CinClare is the first phase III trial using irinotecan combined with neoadjuvant radiochemotherapy for locally advanced rectal cancer treatment under the guidance of UGT1A1 genotype." (PMID 37386467, 2023). "This phase III trial evaluating irinotecan in neoadjuvant CRT for patients with rectal cancer under the guidance of the UGT1A1 genotype has some limitations." (PMID 33119477, 2020). "Understanding the relationship between the UGT1A1 genotype and irinotecan toxicities has renewed interest in therapeutic approaches to rectal cancer." (PMID 33119477, 2020). "In fact, recent research demonstrated genotype-directed irinotecan dosing resulted in improved pathologic complete responses and decreased irinotecan-related toxicity for UGT1A1 intermediate metabolizers (*1/*28) undergoing neoadjuvant chemoradiation for locally advanced rectal cancer." (PMID 34572750, 2021). "In conclusion, under the guidance of the UGT1A1 genotype, an increased irinotecan dose in combination with CRT significantly improved the clinical response rate with acceptable toxicities in Chinese patients with locally advanced rectal cancer." (PMID 33119477, 2020).
small cell lung carcinoma (3 papers, 2021 to 2023). Small cell lung cancer (SCLC) is a highly aggressive malignant neoplasm, accounting for 10-15% of lung cancer cases, characterized byrapid growth, and early metastasis. "In a study on small cell lung cancer, it was shown that UGT1A1*6 and UGT1A1*28 polymorphisms were associated with increased gastrointestinal toxicity and improved OS, respectively." (PMID 35340156, 2022). "For example, UGT1A1 is highly polymorphic and can impact irinotecan (a prodrug used for small cell lung cancer chemotherapy) metabolite related-toxicity." (PMID 37180730, 2023).
ulcerative colitis (3 papers, 2020 to 2026). An inflammatory bowel disease involving the mucosal surface of the large intestine and rectum. "Following dynamic magnetic resonance cholangiopancreatography imaging, colonoscopic manifestation, liver biopsy and whole exome sequencing, the patient was finally diagnosed with PSC - ulcerative colitis with PLKR and UGT1A1 mutation." (PMID 40184140, 2025).
acute kidney injury (2 papers, 2023 to 2025). Sudden and sustained deterioration of the kidney function characterized by decreased glomerular filtration rate, increased serum creatinine or oliguria. "Also, the drug dosage should be strictly controlled in some patients, including patients with severe renal failure and patients with UDP-glucuronosyltransferase 1A1 (UGT1A1) polymorphism." (PMID 37790928, 2023).
acute lymphoblastic leukemia (2 papers, 2008 to 2021). Leukemia with an acute onset, characterized by the presence of lymphoblasts in the bone marrow and the peripheral blood. "Retrospective analysis of a phase I/II clinical trial of nilotinib in patients with BCR-ABL positive CML or acute lymphoblastic leukemia (ALL) found that UGT1A1*28 homozygotes had a significant risk of grade 3/4 hyperbilirubinemia." (PMID 33805415, 2021).
acute myeloid leukemia (2 papers, 2018). Acute myeloid leukemia (AML) is a group of neoplasms arising from precursor cells committed to the myeloid cell-line differentiation. "UGT1A1*6 and *28 polymorphisms resulting in reduced UGT1A1 activity were genotyped in 726 adult acute myeloid leukemia (AML) patients treated with Ara-C based regimens." (PMID 30016963, 2018).
alopecia (2 papers, 2022 to 2024). Hair loss usually from the scalp. "Other TRAEs, including nausea, vomiting, constipation, fatigue, alopecia, and decreased appetite, were not impacted by UGT1A1 variant status." (PMID 36038616, 2022).
dyslipidemia (2 papers, 2024 to 2025). "Schizophrenia patients with UGT1A1*6 mutation and a certain level of baseline bilirubin may be more resistant to dyslipidemia and have more selections for AAPD than other patients." (PMID 38760414, 2024). "When combining the DBIL and UGT1A1*6 as a new parameter to predict dyslipidemia, the power of prediction will be significantly improved (AUC from 0.627 to 0.939)." (PMID 38760414, 2024). "The combination of baseline DBIL and UGT1A1*6 significantly improved the performance in predicting dyslipidemia (AUC = 0.939, p < 0.001)." (PMID 38760414, 2024). "The result of ROC analysis supported the connection between DBIL and UGT1A1 from another angle, and their regulatory effects on dyslipidemia." (PMID 38760414, 2024). "Elevation of serum direct bilirubin (DBIL) within the physiological range, coupled with the presence of the UGT1A1*6 mutation in Chinese patients with schizophrenia, may serve as potential protective factors against AAPD-induced dyslipidemia." (PMID 38760414, 2024). "Furthermore, the odds ratio from multinomial logistic regression analysis showed that UGT1A1*6 was a protective factor for dyslipidemia (ß = −12.868, p < 0.001)." (PMID 38760414, 2024). "So based on our findings, we can expect that when patients with the mutation of UGT1A1*6 and has a DBIL level greater than 4 μmol/L, they may have a certain natural resistance to dyslipidemia induced by antipsychotic drugs." (PMID 38760414, 2024). "Except for dyslipidemia, UGT1A1 may also be related to other side reactions." (PMID 38760414, 2024).
endometrial cancer (2 papers, 2015 to 2021). Primary or metastatic malignant neoplasm involving the endometrium (mucous membrane that lines the endometrial cavity). "Additionally, the MR-Egger intercept test detected overall directional pleiotropy only in the case of endometrial cancer (pintercept = 4 × 10−4) and returned a potential positive association between bilirubin levels, predicted by non-UGT1A1 SNPs, and endometrial cancer (OR 1.37; 95% CI 0.99–1.89)." (PMID 33671849, 2021). "However, the UGT1A1 rs2070959 GG genotype and low soy food intake may decrease the risk of endometrial cancer." (PMID 26114387, 2015).
epilepsy (2 papers, 2017 to 2019). A brain disorder characterized by episodes of abnormally increased neuronal discharge resulting in transient episodes of sensory or motor neurological dysfunction, or psychic dysfunction. "Among the superfamily of UGT enzymes, UGT1 is strongly engaged in the metabolism of drugs used to treat epilepsy (UGT1A4), schizophrenia (UGT1A3 and UGT1A4), hypertension (UGT1A1, UGT1A3, UGT1A7, and UGT1A9), and hypercholesterolemia (UGT1A1 and UGT1A3)." (PMID 30959953, 2019).
HIV-1 infection (2 papers, 2017 to 2022). The type species of lentivirus and the etiologic agent of acquired immunodeficiency syndrome (AIDS). "Therefore, we examined the effects of carrying the UGT1A1*6, *28, or both gene polymorphisms on plasma trough concentrations of DTG in Japanese individuals with HIV-1 infections." (PMID 28915895, 2017).
Hodgkins lymphoma (2 papers, 2021 to 2023). A heterogeneous group of malignant lymphoid neoplasms of B-cell origin characterized histologically by the presence of Hodgkin and Reed-Sternberg (HRS) cells in the vast majority of cases. "A one-standard-deviation rise in circulating bilirubin (4.4 mol/L) predicted by non-UGT1A1 SNPs was inversely linked with a 0.64-fold risk of Hodgkin lymphoma (95% CI 0.42–0.99, p = 0.04) after putative pleiotropic SNPs were eliminated." (PMID 36831357, 2023).
hyperprolactinemia (2 papers, 2023 to 2024). Abnormally high level of prolactin in the blood. "In addition, the polymorphic variant rs887829, rs10929302, and rs111741722 of UGT1A1 were significantly associated with hyperprolactinemia in a study from Thailand74." (PMID 38760414, 2024). "Furthermore, UGT1A1 may also be potentially involved in the metabolic pathway of risperidone since an association between UGT1A1 genetic polymorphisms and risperidone-induced hyperprolactinemia has been established in a clinical study in Thailand." (PMID 38375208, 2023). "Although the exact metabolic role of UGT1A1 in risperidone metabolism has not yet been elucidated, a recent study found a significant association of hyperprolactinemia with UGT1A1 (OMIM ID: 191740) genetic polymorphisms in 84 Thai patients with ASD." (PMID 38375208, 2023).
ischemic stroke (2 papers, 2024). A stroke disorder caused by obstruction of blood flow to the brain, due to thrombotic (local blood clot formation) or embolic (due to a blood clot or other material traveling from another site) event. "The colocalization analysis did not reveal a shared causal variant between indirect bilirubin and the risk of ischemic stroke, based on the examination of 3 genes: UGT1A1, SLCO1B1, and SLCO1B3." (PMID 39210787, 2024).
liver failure (2 papers, 2022 to 2023). A liver disease characterized by the liver losing or has lost all of its function. "The odds ratio of UGT1A1*28 variants was 2.88 with a 95% confidence interval of 1.21–6.84, indicating that UGT1A1*28 variants were associated with cholecystolithiasis in HBV-related liver failure." (PMID 36128448, 2022).
lung squamous cell carcinoma (2 papers, 2021 to 2022). "Polymorphism in the UGT1A1 gene (rs8175347) may contribute as a risk factor for adenocarcinoma and lung squamous cell carcinoma in the population of the Amazon region." (PMID 35328047, 2022).
lymph node metastases (2 papers, 2020 to 2022). "Our retrospective analysis revealed that there was a significant difference in PFS between the UGT1A1 wild-type and polymorphism groups when we analyzed only patients with one or no lymph node metastases." (PMID 32758288, 2020). "Although we recommend CPT-11/NDP to patients with one or no lymph node metastases and UGT1A1 polymorphism, our data do not support recommending this regimen to other patients." (PMID 32758288, 2020). "We believe that it might be beneficial to administer CPT-11/NDP chemotherapy in patients with one or no lymph node metastases and UGT1A1 polymorphism." (PMID 32758288, 2020). "Therefore, we should conduct a prospective study to test the more favorable prognostic effect of the CPT-11/NDP regimen in the UGT1A1 polymorphism group than the wild-type group in cervical cancer patients with one or no lymph node metastases after radical hysterectomy." (PMID 32758288, 2020).
metabolic dysfunction-associated steatotic liver disease (2 papers, 2017 to 2025). Metabolic dysfunction-associated steatotic liver disease (MASLD, formerly known as nonalcoholic fatty liver disease or NAFLD) is a type of liver disease that is not caused by alcohol. "The purpose of this study was to investigate the role of UGT1A1 polymorphism on the metabolism and pharmacokinetics of silymarin flavonolignans in patients with chronic HCV infection or nonalcoholic fatty liver disease (NAFLD)." (PMID 28098838, 2017).
nephrolithiasis (2 papers, 2014 to 2015). The presence of a calculus in the pelvis of the kidney; this is most often composed of mineral salts and proteins. "Indeed, a number of patients already experienced indinavir-associated urolithiasis in our study, another PI that is prone to induce renal calculi and is also an inhibitor of the UGT1A1 pathway." (PMID 25409506, 2014).
osteoporosis (2 papers, 2021 to 2022). A condition of reduced bone mass, with decreased cortical thickness and a decrease in the number and size of the trabeculae of cancellous bone (but normal chemical composition), resulting in increased fracture incidence. "The association of the UGT1A1 on the risk of developing osteopenia and osteoporosis was evaluated, which was then correlated with the clinical parameters, including bone parameters." (PMID 34462452, 2021). "Molecular analysis performed in this study also showed that the heterozygous 6/7 genotype of the UGT1A1*28 variant was slightly less common in women with osteoporosis (46.2%) as compared to healthy controls (51.5%)." (PMID 34462452, 2021). "A significant correlation was observed between the genotypes of the rs3064744 (UGT1A1*28) sequence variant and body mass in women with osteoporosis." (PMID 34462452, 2021). "Analysis of postmenopausal women with osteoporosis revealed that UGT1A1*28 can be used as a marker of bone loss for the timely assessment of bone tissue changes, and that pureton mutations in UGT1A1*28 can reduce the risk of bone loss and osteoporosis in postmenopausal women." (PMID 36741721, 2022). "Our analysis revealed that the UGT1A1 rs3064744 variant may affect the risk of developing osteoporosis in postmenopausal Polish women." (PMID 34462452, 2021). "Our results showed the UGT1A1 rs3064744 (UGT1A1*28) genetic variant may affect the risk of developing osteopenia and osteoporosis in postmenopausal women, especially in the presence of homozygous genotypes containing two mutated alleles." (PMID 34462452, 2021). "The aim of the study was to analyze whether the UGT1A1 genetic variants are associated with the development of osteopenia and osteoporosis in postmenopausal women." (PMID 34462452, 2021). "Moreover, it has been shown that the UGT1A1*28 variant influences glucuronidation of bazedoxifene used for the prevention and treatment of osteoporosis." (PMID 34462452, 2021). "However, the relationship between osteoporosis and the UGT1A1 gene variant in Caucasian postmenopausal women remains to be fully elucidated." (PMID 34462452, 2021). "The aim of the study was to investigate whether the UGT1A1 rs3064744 (UGT1A1*28) and the rs4148323 (UGT1A1*6) genetic variants are associated with the development of osteopenia and osteoporosis in postmenopausal women." (PMID 34462452, 2021). "In conclusion, the results of the present study indicate that the UGT1A1 rs3064744 (UGT1A1*28) genetic variant may affect the risk of developing osteopenia and osteoporosis in postmenopausal women, especially in the presence of homozygous genotypes containing two mutated alleles." (PMID 34462452, 2021). "When comparing the frequency of the analyzed genetic variants and the clinical parameters, a correlation between the genotypes of UGT1A1*28 and body mass was observed in the group of women with osteoporosis." (PMID 34462452, 2021). "The UGT1A1 rs4148323 variant is not directly associated with the development of osteopenia and osteoporosis." (PMID 34462452, 2021). "The UGT1A1 rs4148323 (UGT1A1*6) genetic variant is not directly associated with the development of osteopenia and osteoporosis in postmenopausal Polish women." (PMID 34462452, 2021). "Our findings regarding lack of an association between the UGT1A1*6 variant with osteoporosis are consistent with the observations made in the population of postmenopausal Japanese women." (PMID 34462452, 2021). "Thus, changes in the nucleotide sequence of the UGT1A1 gene might affect the severity and progression rate of osteoporosis." (PMID 34462452, 2021).
schizophrenia (2 papers, 2024 to 2025). A major psychotic disorder characterized by abnormalities in the perception or expression of reality. "In the multinomial logistic regression analysis, we found that the gene mutation about bilirubin metabolism especially UGT1A1*6 plays a protective role in the lipid metabolism of schizophrenia patients after treatment." (PMID 38760414, 2024). "Importantly, emerging research indicates an increased prevalence of UGT1A1 mutations in psychiatric populations, particularly in those with schizophrenia." (PMID 41523389, 2025). "The minimum allele frequencies of different UGT1A1 polymorphisms are discrepant in different races so that the status of bilirubin metabolism may be separate in every ethnic schizophrenia patient in response to the AAPD treatment." (PMID 38760414, 2024). "Gunn rats, which lack functional UGT1A1 enzymes, exhibit behavioral phenotypes akin to schizophrenia, including cognitive impairments and altered sensorimotor gating." (PMID 41523389, 2025).